REN (renin)
Diseases named in the same sentence as REN in open-access papers (continued):
Sharing a sentence is not in itself a finding about the gene and the disease.
primary aldosteronism (continued). "This study was set out before the COVID-19 pandemic to seek for a protective role of the noncanonical branch of the renin–angiotensin system in human primary aldosteronism as ACE-2 has been known for years as a key component of the protective branch of the renin–angiotensin system." (PMID 33657582, 2021). "Notably, her low renin level is somewhat inconsistent with renovascular hypertension (where one would expect an elevated renin), but it does not rule it out, especially if a concurrent primary aldosteronism is suppressing renin release." (PMID 41356982, 2025). "We examined plasma aldosterone concentration (PAC), plasma renin activity (PRA), and clinical characteristics in untreated hypertensive patients without primary aldosteronism, followed for 3 years." (PMID 42162197, 2026). "Another group, “possible” primary aldosteronism, was defined as either ARR ≥ 70 pmol/mIU or taking a medication that affects the RAAS, but not a beta blocker, and renin < 15 mU/L." (PMID 37690031, 2023). "The median BMSi for men with possible primary aldosteronism (ARR ≥ 70 pmol/mIU or taking a RAAS affecting medication except beta blocker and renin < 15 mU/L, n = 19) was also similar to those who did not meet the criteria (85.7 [P25, P75: 79.6–87.4] vs 83.0 [P25, P75: 78.5–87.3], p = 0.459)." (PMID 37690031, 2023).
type 2 diabetes (123 papers, 2004 to 2026). "uDPP4 activity was positively associated with albuminuria, urinary retinol-binding protein 4, LV mass, and type 2 diabetes but inversely associated with body mass index and use of renin-angiotensin system blockers." (PMID 40604004, 2025). "This is particularly important given the frequency of metformin prescription and the common use of renin-angiotensin system blockade in patients with type 2 diabetes, which increases the risk of kidney dysfunction." (PMID 32382466, 2020). "Similar results were obtained from the aliskiren trial in type 2 diabetes using cardio-renal endpoints (ALTITUDE), which compared the effect of a direct renin inhibitor aliskiren to placebo in high-risk type 2 diabetic patients on top of an ACEi or an ARB." (PMID 31212945, 2019). "Activation of the renin-angiotensin-aldosterone-system (RAAS) has been implicated in the development of vascular complications in type 2 diabetes (T2D)." (PMID 27596252, 2016). "In this trial, the inclusion criteria specified patients with type 2 diabetes with over 6.5% of HbA1c and risk factors for the progression of kidney disease, such as albuminuria, who were treated with renin-angiotensin system blockade; enrollment included approximately 60% patients with stage 3 CKD." (PMID 37537531, 2023). "More specifically, we found strong evidence for the effect of ACEIs and ARBs on reducing the risk of new-onset type 2 diabetes, suggesting that renin–angiotensin–aldosterone system deactivation could causally lower the risk of the disease." (PMID 34774144, 2021). "The addition of aliskiren to standard therapy with renin-angiotensin system blockade in patients with type 2 diabetes who are at high risk for cardiovascular and renal events is not supported by the study and may even be harmful." (PMID 31850348, 2019). "Thus, data do not support the addition of aliskiren to standard therapy with renin-angiotensin system blockade in patients with type 2 diabetes who are at high risk of cardiovascular and renal events." (PMID 28725272, 2017). "Therefore, risk factor control in high-risk asymptomatic patients with type 2 diabetes is important, with tight glucose regulation and the use of renin-angiotensin system blockers, aspirin and lipid-lowering agents." (PMID 23978254, 2013). "In addition, individuals with type 2 diabetes were reported to have low baseline plasma renin activity, which may be associated with an increased risk of developing aldosterone escape." (PMID 28066329, 2016). "In individuals with type 2 diabetes, aquatic walking/running acutely reduces plasma renin levels to a greater extent than dry-land walking/running, while eliciting similar reductions in the glycemic response between environments." (PMID 39063514, 2024). "Adding esaxerenone to the existing renin-angiotensin system inhibitor therapy in patients with type 2 diabetes and microalbuminuria has shown to increase the likelihood of the normalization of the albumin levels and reduced progression of albuminuria." (PMID 36704237, 2023). "The renin–angiotensin–aldosterone system is pathologically activated in type II diabetes; this has been noted to result in various detrimental effects, including osteoporosis and estrogen deficiency." (PMID 37569338, 2023). "In patients with type 2 diabetes and preserved kidney function, dapagliflozin increases plasma renin levels at 2, 6, and 12 weeks." (PMID 38155663, 2023). "KEGG pathways, such as addiction signaling cytochrome p450, maturity-onset diabetes, complement coagulation cascades, renin-angiotensin system, and pathways regulating pluripotency cells were enriched (p < 0.05)." (PMID 36246622, 2022). "Pine nut protein offers promise for type-2 diabetes with hypoglycaemic activity, while cashew nut protein peptides have exhibited antioxidant activity and cardiovascular benefits via the renin-angiotensin system." (PMID 35206005, 2022).
type 2 diabetes (continued). "Two out of four studies assessed the impact of direct renin inhibitors on eGFR including overall 9,160 patients with type 2 diabetes." (PMID 36204481, 2022). "In this regard, in a model of type 2 diabetes, dapagliflozin decreased the renal expression of the renin–angiotensin system (RAS), oxidative stress, renal inflammation, and fibrosis." (PMID 35270028, 2022). "Anti-hypertensive treatments on sPRR, renin activity, and urine prorenin differ between men and women with type 2 diabetes." (PMID 33933156, 2021). "The Renin-Angiotensin System (RAS) system regulates blood pressure; its overactivity is reported in metabolic syndrome, obesity and type 2 diabetes (T2D), all high-risk conditions for severe COVID-19 disease." (PMID 33521617, 2021). "Plasma renin activity (PRA) was significantly higher in participants with type 2 diabetes compared to controls." (PMID 33933156, 2021). "The currently approved medication to protect kidney function in patients with type 2 diabetes mellitus (T2DM) is renin-angiotensin system inhibitor (RASI)." (PMID 34289813, 2021). "Urine renin activity was increased among men and women with type 2 diabetes treated with blood pressure medications." (PMID 33933156, 2021). "Both women and men showed increased urine renin activity; however, the increase was greater in men than in women with type 2 diabetes." (PMID 33933156, 2021). "Renin-angiotensin-aldosterone system inhibitor (RAASi) is effective in protecting against the progression of nephropathy due to type 2 diabetes (T2D)." (PMID 33990175, 2021). "In the present study, patients with type 2 diabetes had greater increases in renin activity in the urine." (PMID 33933156, 2021). "These SNPs were reported to have a tight link with multiple disorders, including blood pressure and renin response to dietary salt intake, and type 2 diabetes, with the possibility to affect the process of splicing, processing, and editing of mRNA." (PMID 31632443, 2019). "We conducted a descriptive case study to examine the effects of sodium-glucose cotransporter 2 (SGLT2) inhibitors on urinary angiotensinogen excretion, which represents the function of the intrarenal renin–angiotensin system, in patients with type 2 diabetes." (PMID 28596160, 2017). "The concentrations of leptin in both P and PF were each related to type 2 diabetes, BMI, circulating levels of glycated hemoglobin and to treatment with an inhibitor of the renin-angiotensin system." (PMID 27139713, 2016). "Patients with nonalcoholic steatohepatitis (NASH) had similar demographic and anthropometric features, but a higher prevalence of type 2 diabetes (T2D; p = 0.010), and use of renin-angiotensin axis system (RAS) inhibitors (p = 0.005)." (PMID 27649410, 2016). "Activation of the renin-angiotensin-aldosterone-system (RAAS) has been proposed to contribute to development of vascular complications in type 2 diabetes (T2D)." (PMID 27596252, 2016). "Selective vitamin D receptor activator paricalcitol effectively reduce proteinuria in patients with type 2 diabetes through inhibition of the renin-angiotensin-aldosterone system (RAAS)." (PMID 26109389, 2015). "Increases in plasma aldosterone concentrations and renin activity have also been reported when empagliflozin is administered to patients with type 1 diabetes and when dapagliflozin is administered to patients with type 2 diabetes." (PMID 36983252, 2023). "The FIDELIO-DKD study showed that finerenone, a non-steroidal selective mineralocorticoid receptor antagonist, lowered the risks of CKD progression and cardiovascular events in people with CKD and type 2 diabetes treated optimally with renin-angiotensin system blockade." (PMID 34979961, 2022). "In recent research, Ferrannini and co-workers analyzed plasma proteins by aptamer assays and reported that GDF15, renin, and adiponectin may be shared markers of type 2 diabetes (T2D) and CAD." (PMID 36312558, 2022).
type 2 diabetes (continued). "Similarly, the renin activity was increased in the urine of subjects with type 2 diabetes compared to controls." (PMID 33933156, 2021). "We did not quantify the levels of Ang-II in urine, but the concomitant augmentation of renin activity and uAGT, particularly from men with type 2 diabetes, emphasizes the importance of intrarenal and intratubular RAS activation in the progression of DN and CKD." (PMID 33933156, 2021). "The prevalence of type 2 diabetes is higher among African Americans, where activation of the renin–angiotensin–aldosterone system may play a significant role." (PMID 34350730, 2021). "In the present study, the fact that renin activity measured by radioimmunoassay was increased in urine four- and three-fold in men and women with type 2 diabetes, respectively, suggests that active renin was probably generated further down in the distal nephron segments." (PMID 33933156, 2021). "The demonstration that sPRR in urine-positive correlates with eGFR in men but not in women suggest that urine sPRR in men with type 2 diabetes might be associated with the stimulation of urine renin activity and eGFR decline over time." (PMID 33933156, 2021). "Therefore, a post hoc analysis was performed on two randomized controlled trials (n = 69), assessing effects of dapagliflozin 10 mg/day when added to renin–angiotensin system inhibition in patients with type 2 diabetes and urinary albumin-to-creatinine ratio ≥30 mg/g." (PMID 31159350, 2019). "The combination of SGLT2is with renin–angiotensin system blockers, including ACE inhibitors and ARBs, has synergistic effects on the treatment of type 2 diabetes mellitus (T2DM)." (PMID 40630104, 2025). "Previous studies have shown a link between the renin–angiotensin system (RAS) and adipose tissue dysfunction in type 2 diabetes (T2D); however, the role of RAS in prediabetes remains underexplored." (PMID 40564980, 2025). "Obesity is associated with increased activity of the systemic and tissue renin‐angiotensin‐aldosterone system (RAAS), which plays an important role in the development of insulin resistance, hypertension, type 2 diabetes (T2D), and cardiovascular disease." (PMID 39317676, 2024). "Three out of four included studies assessed the impact of direct renin inhibitors on UACR involving overall 9,262 patients with type 2 diabetes." (PMID 36204481, 2022). "Both acute GLP-1 infusion and a single liraglutide dose decreased plasma ANG II concentration in healthy subjects and type 2 diabetic patients, consistently with an inhibitory effect of GLP-1 on renin secretion." (PMID 34745006, 2021). "Moreover, the increase in plasma renin activity induced by the angiotensin receptor blocker suggested that there might be increased intrarenal angiotensin II production suppressing plasma renin activity in type 2 diabetes." (PMID 28066329, 2016). "Increased activation of the renin-angiotensin system (RAS) may be important in promoting coronary heart disease (CHD) and renal dysfunction, but limited data are available on associations between angiotensin type 1 receptor (AGT1R) and angiotensinogen (AGT) genotypes in type 2 diabetes." (PMID 19327134, 2009). "Additionally, the inhibition of the renin-angiotensin system with ACE inhibitors and angiotensin receptor blockers not only regressed LVH, but also delayed the onset of type 2 diabetes." (PMID 38167639, 2024). "In contrast, another study showed that dapagliflozin and empagliflozin did not significantly increase plasma renin activity and aldosterone levels at 30 and 90 days in patients with type 2 diabetes." (PMID 38155663, 2023). "In contrast, there is a report of no change in renin activity and aldosterone levels in a patient with type 2 diabetes treated with empagliflozin for 5 days." (PMID 36983252, 2023).
type 2 diabetes (continued). "Pharmacological blockade of the renin–angiotensin–aldosterone system (RAAS) using angiotensin-converting enzyme inhibitors (ACEi) and angiotensin receptor blockers (ARB) has become the cornerstone for patients with type 2 diabetes (T2D) and kidney involvement." (PMID 37959333, 2023). "In obesity-related disorders, such as type 2 diabetes (T2DM), the renal NO− bioavailability is impaired, which increases renin secretion, intraglomerular pressure, tubuloglomerular feedback, and renal sodium reabsorption, while renal blood flow perfusion is reduced." (PMID 34621463, 2021). "The renin-angiotensin system (RAS) is critical in the regulation of glycolipid metabolism and insulin sensitivity, which are closely related to metabolic syndromes [e.g., obesity, type 2 diabetes mellitus (T2DM), and non-alcoholic fatty liver disease (NAFLD)]." (PMID 32322207, 2020). "The double-blind, double-dummy trial randomized 818 adults with CKD and type 2 diabetes [urine albumin–creatinine ratio (UACR) ≥100 to <5000 mg/g] to receive once-daily finerenone plus empagliflozin, finerenone alone or empagliflozin alone, all in addition to a renin–angiotensin system inhibitor." (PMID 40886054, 2025). "Patients with type 2 diabetes and CKD (urinary albumin-to-creatinine ratio [UACR] of ≥30 to <300 mg/g and estimated glomerular filtration rate [eGFR] of ≥25-≤90 mL/min/1.73 m2, or UACR of ≥300 to ≤5,000 and eGFR of ≥25 mL/min/1.73 m2) on optimized renin–angiotensin system blockade." (PMID 37745646, 2023). "Urine renin activity may reflect the severity of kidney dysfunction, which emphasizes its importance as a potential marker of maladaptive intrarenal/intratubular RAS activation in patients with type 2 diabetes." (PMID 33933156, 2021). "Therefore, we cannot rule out that the augmentation of renin activity and prorenin in the urine of patients with type 2 diabetes is due to altered glomerular filtration and/or impaired proximal tubular reabsorption." (PMID 33933156, 2021). "Therefore, it was proposed that plasma renin might not reflect intrarenal renin levels in type 2 diabetes." (PMID 28066329, 2016). "Two Tables are presented showing the associations of vasoactive prohormones with the aldosterone to renin ratio (ARR) in subjects with and without diabetes type 2 or prediabetes in a population-based cohort." (PMID 27595128, 2016).
Hyponatremia (116 papers, 2010 to 2026). An abnormally decreased sodium concentration in the blood. "Hyponatremia stimulates the synthesis of renin and causes a decrease in the ratio, while high levels of sodium in the blood profoundly inhibit the synthesis of renin and cause an increase in ARR." (PMID 32025248, 2019). "Additionally, any drug that interferes with the renin–angiotensin–aldosterone system (RAAS) has the potential to increase the risk of hyponatremia." (PMID 41010788, 2025). "The mechanisms dependent on hyponatremia and responsible for a worse prognosis in acute MI patients can be associated with the release of vasopressin, and the activation of the sympathetic and renin– angiotensin–aldosterone systems." (PMID 39941632, 2025). "Plasma renin levels were significantly increased in patients with arterial hypotension and hyponatremia and renin was independently associated with serum sodium concentration, suggesting renin release upon impaired kidney perfusion or due to reduced sodium concentration sensed by the macula densa." (PMID 34021479, 2021). "Here, we present the case of a patient with recurrent, refractory hyponatremia due to hypoaldosteronism with normal serum renin activity and cortisol levels." (PMID 42117122, 2026). "Hyponatremia in acute heart failure occurs due to decreased cardiac output, reduced kidney perfusion, and activation of the renin-angiotensin-aldosterone system (RAAS) and sympathetic nervous system, causing sodium and water retention." (PMID 41388514, 2025). "The neurohumoral response restores the arteries fulling through the activation of renin–angiotensin and the increase in vasopressin secretion, mediates the reabsorption of electrolyte-free water in the kidney, and subsequently inclines hyponatremia." (PMID 38610725, 2024). "Multiple neurohormonal changes generally cause hyponatremia in patients with ADHF, particularly renin-angiotensin aldosterone system (RAAS) activation to stimulate the release of arginine vasopressin." (PMID 37884881, 2023). "The main interactions among the three involve neurohormone-induced hyponatremia, renin-angiotensin-aldosterone system activation, retention of water and sodium, links to fluid overload, and atrial myocardial stretch facilitation of AF." (PMID 36312256, 2022). "The renin-angiotensin system (RAS) is an important counter-regulatory mechanism to prevent hyponatremia under LS conditions." (PMID 36359330, 2022). "Hyponatremia is a well-known marker of neurohormonal activation in patients with left-sided heart failure and is highly correlated with plasm norepinephrine, renin, and angiotensin II levels, being also a marker of right ventricular dysfunction." (PMID 33535666, 2021). "Hyponatremia is known to be a marker of dysregulation of the renin‐angiotensin system in acute and chronic CVD and has been associated with increased mortality in several studies." (PMID 33277922, 2021). "The classic mechanisms of hyponatremia like the activation of the renin–angiotensin–aldosterone system and elevated catecholamine levels in heart failure leading to vasoconstriction and decreased glomerular filtration rate are well known." (PMID 33535666, 2021). "Hyponatremia rate in Fontan patients was reported to be 30% due to high dose of diuretics, elevated renin activity and norepinephrine levels, and was reported as an independent predictor of unscheduled readmissions." (PMID 32369294, 2020). "In contrast, hyponatremia in Hispanics, although implicating a poor prognosis in HF, connotes a less critical state from their higher plasma renin activity." (PMID 31216316, 2019). "A laboratory workup revealed severe hyponatremia, hyperkaliaemia and high plasma renin with unappropriated normal plasma aldosterone levels, raising the suspicion of AS deficiency." (PMID 30864636, 2019).